REN (renin)
Diseases named in the same sentence as REN in open-access papers (continued):
Sharing a sentence is not in itself a finding about the gene and the disease.
Hypokalemia (continued). "The cancer-derived PGE2 might increase renin secretion in kidney and cause severe preoperative hypokalemia." (PMID 28498361, 2017). "Laboratory findings revealed persistent hypokalemia, metabolic alkalosis, suppressed renin, and inappropriately elevated aldosterone." (PMID 42058696, 2026). "Biochemical studies revealed hypokalemia, metabolic alkalosis, raised urinary potassium levels and raised serum renin." (PMID 40666068, 2025). "The diagnosis is further supported by low serum aldosterone and plasma renin in addition to hypokalemia despite an elevated urinary potassium-creatinine ratio." (PMID 40115718, 2025). "Case 2: exhibited a complex clinical picture reminiscent of Bartter syndrome, including persistent hypokalemia, metabolic alkalosis, and salt wasting with elevated plasma renin and aldosterone levels." (PMID 41427162, 2025). "Hypokalemia, resulting from hyperaldosteronism, exacerbates renin secretion, thus intensifying the vicious circle." (PMID 40493279, 2025). "Biochemical success is defined as correction of hypokalaemia (if hypokalaemia was present pre-procedure) and normalisation of the aldosterone-renin ratio (ARR) or a positive aldosterone suppression test." (PMID 41439054, 2025). "The algorithm with the highest specificity (98%) for unilateral PA consisted of an adrenal nodule on CT, plasma aldosterone concentration >20.0 ng/dL (554 pmol/L), hypokalaemia (≤3.5 mmol/L) and renin concentration ≤5 mIU/L." (PMID 41066498, 2025). "Laboratory tests typically show significantly elevated plasma renin levels, hypokalemia, and hyperaldosteronism." (PMID 40989803, 2025). "Here, we report five unrelated patients with PHP1B who were initially misdiagnosed with GS due to overlapping clinical features—namely, hypokalemia, hypocalcemia, and elevated renin activity." (PMID 40893942, 2025). "Our patient's findings of recurrent pregnancy with severe hypokalemia, gestational hypertension, suppressed renin and aldosterone, and elevated urine potassium-creatinine ratio support the diagnosis of Geller syndrome." (PMID 40115718, 2025). "Clinically, this is characterized by high urinary excretions of sodium, chloride, potassium, and magnesium leading to activation of the renin-angiotensin system, hypokalemia, metabolic alkalosis, and hypomagnesemia." (PMID 41278357, 2025). "Typical biochemical findings are metabolic alkalosis and the “five lows and one high”: hypokalemia, hypomagnesemia, hypochloremia, hypocalciuria, hypotension, and heightened renin–angiotensin–aldosterone system activity." (PMID 40898507, 2025). "In patients with suppressed renin concentration, spontaneous hypokalemia, and plasma/serum aldosterone concentration ≥ 20 ng/dL (≥ 555 pmol/L) confirmatory test is not needed." (PMID 40309437, 2025). "The contribution of hypokalemia and the activated renin-angiotensin system to kidney injury in GS remains to be determined." (PMID 41278357, 2025). "In retrospect, the persistently suppressed renin and hypokalemia were red flags for coexisting primary hyperaldosteronism." (PMID 41356982, 2025). "Laboratory findings indicated that the GS subject presented with hypokalemia, metabolic alkalosis, hypomagnesemia, hypocalciuria, elevated concentrations of plasma renin activity and aldosterone." (PMID 39934873, 2025). "Her laboratory investigations revealed mild hypokalemia with metabolic alkalosis and low renin and aldosterone values." (PMID 39301344, 2024). "In patients with hypertensive hypokalemia, the presence of aldosteronism should be evaluated by testing plasma aldosterone concentrations and plasma renin activity." (PMID 38491421, 2024). "Prolonged licorice consumption precipitates cortisol-induced mineralocorticoid effects, manifesting as hypoaldosteronism-like symptoms, including reduced renin levels, sodium retention, hypokalemia, elevated blood pressure, and metabolic alkalosis." (PMID 40757677, 2024).
Hypokalemia (continued). "Labs showed elevated serum creatinine, hypokalemia, metabolic alkalosis, elevated renin and aldosterone and hypercalciuria." (PMID 38165475, 2024). "Characteristic features include hypokalemia, metabolic alkalosis, suppressed plasma renin activity, and low plasma aldosterone." (PMID 38786976, 2024). "In cases of severe vomiting and nasogastric suctioning, volume depletion contributes to hypokalemia by activating the renin-angiotensin-aldosterone system, which enhances renal potassium wasting." (PMID 38953091, 2024). "After SABR, the patient had progressive improvement of pain, reduction in antihypertensive drugs, control of blood pressure and hypokalemia, normalization of serum aldosterone and renin levels, and reduction in tumor size and weight." (PMID 39420904, 2024). "Initial AVS indicated ABAS, but unilateral PA remained possible due to elevated aldosterone, low renin, hypokalemia, and a right adrenal nodule (8 × 7 mm) on computed tomography." (PMID 39286517, 2024). "Confirmatory tests were omitted in patients with overt PA (markedly elevated aldosterone level, suppressed renin, and spontaneous hypokalemia)." (PMID 38261997, 2024). "Blood tests showed hypokalemia (potassium 3.4 mmol/L) with an elevated plasma aldosterone concentration of 1050 pmol/L (38 ng/dL) and direct renin concentration of 11 mU/L." (PMID 38887633, 2024). "This condition is characterized by low plasma renin activity, hypokalemia, metabolic alkalosis, hypercalciuria, and nephrocalcinosis." (PMID 38691164, 2024). "Laboratory testing showed hypokalemia and elevated plasma aldosterone concentration with suppressed renin." (PMID 38505749, 2024). "This disorder is characterized by moderate to severe early-onset AH, low plasma renin, mild hypokalemia despite high aldosterone levels, and metabolic alkalosis." (PMID 38786976, 2024). "Although usually less severe, hypokalemia in Gitelman syndrome, as in BS, is secondary to the activation of the renin-angiotensine aldosterone system, which increases the secretion of potassium in the collecting duct." (PMID 37537162, 2023). "PA results from the excessive production of aldosterone independently of renin and angiotensin II and leads to increased renal tubular resorption of sodium and volume expansion, resulting in increased blood pressure and hypokalaemia." (PMID 37810894, 2023). "The biochemical evaluation revealed elevated plasma aldosterone concentrations with low plasma renin activity, diuretic-induced hypokalemia, and metabolic alkalosis." (PMID 37485117, 2023). "This monogenic form is commonly associated with electrolyte disturbances and manifested as refractory hypertension, hypokalaemia, metabolic alkalosis, and low renin levels." (PMID 37201134, 2023). "Hypokalemia, metabolic alkalosis, hypomagnesemia, hypocalciuria, and renin-angiotensin-aldosterone system (RAAS) activation are characteristics of GS." (PMID 37791211, 2023). "Gitelman syndrome is characterized by hypokalemia, metabolic alkalosis, hypomagnesemia, hypocalciuria, and renin-angiotensin-aldosterone system (RAAS) activation, and is caused by variants in the SLC12A3 gene." (PMID 37377595, 2023). "These usually share hypokalemia as a common biochemical sign, which is secondary to the activation of the renin-angiotensin aldosterone system due to excessive sodium and water loss." (PMID 37537162, 2023). "In this study, 13 children with RVH had hypokalemia, and most of them were accompanied by high renin levels." (PMID 36461036, 2022). "PA screening should be performed with plasma aldosterone (A) and renin (R) measurements, with hypokalemia correction before the test." (PMID 35813615, 2022). "Several studies have shown that both confirmatory testing as well as AVS can be avoided in full-blown UHA patients with a markedly high PAC, a reduced plasma renin level, spontaneous hypokalemia, and a unilateral hypodense adrenal tumor." (PMID 35388294, 2022).
Hypokalemia (continued). "It is characterized by early-onset refractory hypertension, hypokalemia, low renin activity, and hypoaldosteronism." (PMID 35774371, 2022). "In the postoperative biochemical tests, hypokalemia was resolved; however, the aldosterone to renin ratio (ARR) remained high." (PMID 34572956, 2021). "Due to the low rate of aldosterone secretion, recent guidelines recommend the use of aldosterone/renin ratio to exclude primary aldosteronism only in patients with adrenal tumors and concomitant hypertension or unexplained hypokalemia." (PMID 34567112, 2021). "Hypokalemia, borderline low renin levels, high ACTH levels, and decreased 17 hydroxyprogesterone, estradiol, testosterone, androstenedione, dehydroepiandrosterone sulfate (DHEA-S), and cortisol levels were observed in the proband and her older sister." (PMID 34290232, 2021). "The medically treated patients, owing to an intensification of the multiple drug treatment, showed a rise of renin, the normalization of high BP, along with correction of the hypokalemia." (PMID 34682878, 2021). "Both probands showed hypokalemia, hypomagnesemia, hypocalcinuria, metabolic alkalosis, blood renin, and angiotensin activation state, and proband A showed decreased urine chloride and phosphorus with increased magnesium ion excretion and thyroid dysfunction." (PMID 34046503, 2021). "Aldosterone-secreting tumors cause the so-called “Conn's syndrome” or primary hyperaldosteronism, which is characterized by resistant hypertension and hypokalemia with an abnormal aldosterone/renin ratio." (PMID 34567112, 2021). "Patients with a combination of a high PAC (>20 ng/dL), sufficient renin suppression and spontaneous hypokalemia at screening can directly proceed with the discriminative step by skipping the confirmatory step." (PMID 33802814, 2021). "The reliability of the endocrinological evaluation is preserved when the testing conditions are set as under unrestricted salt diet and after correction of hypokalemia and adjustment of medications interfering the renin-angiotensin-aldosterone system (RAAS)." (PMID 33802814, 2021). "Another female patient was reported to have growth retardation with persistent hypokalemia, hypomagnesemia, hypocalciuria, hypochloremic alkalosis and elevated levels of plasma renin and aldosterone." (PMID 33807568, 2021). "This tends to suppress the renin-angiotensin-aldosterone system via blood pressure increase and hypokalaemia." (PMID 34524979, 2021). "If ARR is abnormal (elevated), a confirmatory test is needed, except for patients with spontaneous hypokalemia, plasma renin below the detection threshold and plasma aldosterone >20 ng/dl." (PMID 34054559, 2021). "This condition is suggested based on the fact that the presence of an elevated PAC and/or hypokalemia reduces false-positive results in ARR rendered by very low renin levels." (PMID 33802814, 2021). "Spontaneous hypokalemia and undetectable renin level along with a very high aldosterone level confirm the diagnosis of PA." (PMID 32665023, 2020). "In clinical pictures characterized by metabolic alkalosis and hypokalemia, the evaluation of renin, aldosterone and blood pressure is crucial for accurate diagnosis." (PMID 33167351, 2020). "The ratio of aldosterone level to renin activity tended to be higher in patients with hypokalemia with hypernatremia." (PMID 33121430, 2020). "SAME is an autosomal recessive disorder of 11-beta HSD2 deficiency characterized by severe HTN with target organ damage, hypercalciuria, nephrocalcinosis, hypokalemia, and metabolic alkalosis with low levels of plasma renin and aldosterone levels." (PMID 33194923, 2020). "Gitelman syndrome is characterized by hypokalemia, metabolic alkalosis, hypomagnesemia, hypocalciuria, and renin-angiotensin-aldosterone system (RAAS) activation." (PMID 32758178, 2020). "The ratio of aldosterone level to renin activity tended to be high in patients with hypokalemia with hypernatremia." (PMID 33121430, 2020).
Hypokalemia (continued). "Bartter syndrome is the most important genetic disorder to consider in the differential diagnosis of Gitelman syndrome, since both exhibit hypokalemia, metabolic alkalosis, and increased plasma renin activity and aldosterone levels with normal blood pressure." (PMID 32758178, 2020). "Both children showed severe phenotypes with growth delay, vomit, anorexia and dehydration, high levels of renin and aldosterone, and hypokalemia." (PMID 32256370, 2020). "The following biochemical profile confirmed the diagnosis since there was spontaneous hypokalemia, undetectable renin, and a PAC above 20 ng/dL." (PMID 32665023, 2020). "Remarkable blood and urine findings included hypokalemia, hypomagnesemia, hypochloremic metabolic alkalosis, hyperuricemia, high blood levels of renin and aldosterone, and hypocalciuria." (PMID 32256370, 2020). "A saline load confirmatory test was not performed as he presented with the following: spontaneous hypokalemia, plasma renin level measuring below detection levels, and a plasma aldosterone level above 20 ng/dL." (PMID 32665023, 2020). "The presentation of the following confirms the diagnosis of primary aldosteronism: spontaneous hypokalemia, an undetectable renin level, and a high aldosterone level." (PMID 32665023, 2020). "Plasma aldosterone concentration was high in some patients and normal in others owing to a combination of the stimulatory effect of renin and the inhibitory effect of hypokalemia on aldosterone production." (PMID 31472005, 2019). "Over the course of mifepristone treatment, she developed hypokalemia, and spironolactone was initiated and titrated up to 100 mg twice daily, based on potassium and plasma renin activity." (PMID 31112270, 2019). "Contraindications to their implementation are the aldosterone-to-renin ratio in plasma above 50, the combination of spontaneous hypokalemia and aldosterone levels greater than 20 ng/dl (550 pmol/l), low or not determined, direct plasma renin or its activity." (PMID 32025248, 2019). "Differential diagnosis included mineralocorticoid or apparent mineralocorticoid excess diseases, with a high aldosterone-to-renin ratio (ARR) after correcting hypokalemia." (PMID 29514039, 2018). "Laboratory test showed severe hypokalemia, hypomagnesemia, hypocalciuria, and metabolic alkalosis, along with elevated renin activity." (PMID 29378538, 2018). "Six patients with spontaneous hypokalemia, undetectable renin concentrations, and PAC > 20 ng/dl were included as PA, even though no further confirmatory testing was performed." (PMID 30123268, 2018). "Workup for hypokalemia yielded aldosterone 5.3 ng/dL (<31 ng/dL), renin 0.6 ng/mL/h (0.5-4 ng/mL/h), and 6:00 a.m." (PMID 29755405, 2018). "Both patients presented with hypokalemia and further investigations revealed hyperaldosteronism with unsuppressed renin levels." (PMID 30410790, 2018). "Patients with GRA typically present with mild hypokalemia, metabolic alkalosis, and low plasma renin levels." (PMID 29404309, 2017). "Patients with Liddle syndrome typically present with hypokalemia, metabolic alkalosis, low renin and aldosterone levels, and early onset HTN." (PMID 29404309, 2017). "PA is characterized by an autonomous aldosterone production causing sodium retention, plasma renin supression, HTN, cardiovascular damage, and increased potassium excretion, leading to variable degrees of hypokalemia." (PMID 28699986, 2017). "This autonomous aldosterone production causes sodium retention, plasma renin supression, HTN, cardiovascular damage, and increased potassium excretion, leading to variable degree of hypokalemia." (PMID 28699986, 2017). "The loss-of-function mutation of HSD11B2 leads to cortisol-dependent activation of the MR resulting in sodium retention, hypokalemia, metabolic alkalosis, suppressed renin and aldosterone levels and increased cortisol/cortisone ratio." (PMID 28587112, 2017).
Hypokalemia (continued). "Liddle’s syndrome leads to hypokalemia, suppressed renin and aldosterone levels and a severe increase of BP, often resistant to anti-hypertensive agents, during childhood." (PMID 28587112, 2017). "It is important to differentiate GS from classic Bartter's syndrome which is also characterized by hypokalemia, renal potassium wasting, and activation of the renin-angiotensin-aldosterone axis." (PMID 27579038, 2016). "An exception to the confirmatory test suggestion is in the case of subjects with spontaneous hypokalemia, plasma renin below detection levels plus PAC>20 ng/dL (550 pmol/L)." (PMID 28018978, 2016). "Renin converts angiotensin I into angiotensin II, leading to water retention, hypernatremia and hypokalemia." (PMID 26893366, 2016). "A previously healthy 7‐year‐old male presented with hypertensive emergency, hypokalemia, and elevated plasma renin activity and aldosterone levels." (PMID 26997629, 2016). "Renovascular hypertension should be suspected in children with suspected secondary HTN, as well as in those with raised peripheral plasma renin, moderate hypokalemia, or HTN so severe that it requires more than two agents to normalize the BP." (PMID 26000267, 2015). "The patient was found to have hypochloremic metabolic alkalosis with hypokalemia and elevated serum levels of renin and aldosterone." (PMID 26157392, 2015). "Hypokalemia was also reported to stimulate renin and angiotensin II despite direct suppression of aldosterone synthesis leading to salt-sensitive hypertension, intrarenal vasoconstriction and ischemia." (PMID 23843989, 2013). "Patients with classic BS fail to thrive from infancy and exhibit hypokalemia, metabolic alkalosis, hyperactive renin-aldosterone system, and overproduction of prostaglandins." (PMID 24377430, 2013). "If 11-beta hydroxysteroid (HSD2) is oversaturated or defective, more cortisol will be available to bind MCR, a condition termed as apparent MC excess (AME), characterized by low renin and aldosterone levels, normal plasma cortisol level, and hypokalemia." (PMID 22957211, 2012). "The presence of metabolic alkalosis, hypokalemia, hypochloremia, and high renin and aldosterone levels were suggestive of Bartter syndrome and a treatment regimen for Bartter syndrome was started." (PMID 21750641, 2011). "Endocrinological investigation, revealed marked hypokalemia (serum potassium: 2.7 mEq/l), suppressed renin levels, increased aldosterone levels with an aldosterone/renin ratio >30, findings suggestive of primary hyperaldosteronism." (PMID 20181215, 2009). "Biochemical investigations show elevated aldosterone, suppressed renin, and hypokalaemia." (PMID 40540150, 2025). "Moreover, refractory hypokalemia can be seen in Gitelman and Bartter syndrome; however, normal or low blood pressure with elevated renin and aldosterone levels is expected in patients who are diagnosed with these syndromes." (PMID 40115718, 2025). "Additionally, stroke can induce aldosterone hypersecretion, which overactivates the renin–angiotensin–aldosterone system (RAAS), accelerating renal potassium excretion and causing hypokalemia." (PMID 40308225, 2025). "Gitelman’s syndrome, also known as, familial hypokalemia–hypomagnesemia, is a renal tubulopathy responsible for salt wasting resulting in, hypomagnesemia, hypocalciuria, and secondary activation of the renin–angiotensin–aldosterone system, responsible for the hypokalemia and metabolic alkalosis." (PMID 40547410, 2025). "In addition to being prone to hyponatraemia, patients with these conditions often experience potassium abnormalities, including hyperkalaemia and hypokalaemia, due to the use of renin–angiotensin system inhibitors and potassium-wasting diuretics." (PMID 41383907, 2025). "Initial evaluation revealed hypokalemia and metabolic alkalosis with an aldosterone-to-renin ratio suggestive, but not diagnostic, of primary hyperaldosteronism." (PMID 41356982, 2025).